MMP9 (matrix metallopeptidase 9)
Diseases named in the same sentence as MMP9 in open-access papers (continued):
Sharing a sentence is not in itself a finding about the gene and the disease.
Cerebral ischemia (continued). "MMP9 plays a role in the inflammatory response following cerebral ischemia." (PMID 37927954, 2023). "In focal brain ischemia models, MMP-9 KO mice showed noteworthy BBB protection." (PMID 36729260, 2023). "Considering that miR-21 plays a key role in the occurrence and development of MMP9-mediated cerebral ischemia, anti-miR-21 may become a new effective intervention to prevent the formation of post-ischemic lesions." (PMID 35173580, 2022). "MMP9 increases rapidly after cerebral ischemia and hypoxia, destroying the integrity of the vascular wall by degrading tight junctions and the extracellular matrix to increase the BBB permeability, and further leading to neuronal death, cerebral edema, and hemorrhagic transformation." (PMID 36061592, 2022). "Therefore, MMP9 can be used as a blood detection marker in the prediction of hemorrhagic transformation of patients, and the high expression level of MMP9 after cerebral ischemia is more likely to lead to hemorrhagic transformation after ischemia." (PMID 34313877, 2022). "MMP‐9 is known to play a key role in cerebral ischemia reperfusion and may be a new therapeutic target." (PMID 34591349, 2022). "In addition, a variety of drugs targeting MMP-2 and MMP-9 have protective effects on the brain in the mice with cerebral ischemia/reperfusion injury." (PMID 35462697, 2022). "The results of clinical research on patients with cerebral ischemia suggested that the expression level of MMP9 in human cerebral ischemia patients was higher than that in healthy people, and the expression level of MMP9 was also closely related to the prognosis of patients with cerebral ischemia." (PMID 34313877, 2022). "miR-21 was shown to be significantly upregulated in the rat hippocampus following cerebral ischemia, while an antagomir of miR-21 could decrease the MMP9 protein level after cerebral ischemia." (PMID 35173580, 2022). "Calcium signal stimulation may trigger the extracellular signal-regulated kinase signaling pathway by regulating miR-21, which leads to the upregulation of MMP9 after cerebral ischemia." (PMID 35173580, 2022). "However, the levels of MMP-9 are elevated after cerebral ischemia, and MMP-9 levels are closely related to the occurrence and development of cerebral infarction." (PMID 36127663, 2022). "In addition, a high concentration of ROS induced by cerebral ischemia–reperfusion can activate MMP-9 to aggravate the BBB damage and lead to cell death by lipid peroxidation, protein dysfunction, and DNA damage." (PMID 35359227, 2022). "Estrogens also could modulate the activity of MMPs such as MMP-2 and MMP-9 in ovariectomized rats under cerebral ischemia-reperfusion injury." (PMID 35432799, 2021). "Furthermore, HMGB1 has been shown to activate TLR4 to induce MMP-9 upregulation following cerebral ischemia." (PMID 33487119, 2021). "Moreover, high-mobility group box 1 (HMGB1) is released resulting in TLR4-dependent MMP-9 upregulation in the brain following cerebral ischemia in mice." (PMID 33487119, 2021). "Furthermore, photothrombotic mouse models of cerebral ischemia have reported that BBB permeability at the level of the capillary is governed by pericytes exhibiting MMP-9 activation, which was later neutralized by specific MMP-9 inhibition." (PMID 34566627, 2021). "There is evidence indicating that inflammatory cells, such as neutrophils release matrix metalloproteinases-9 (MMP-9) or other MMPs, suggesting that antiinflammatory drugs may decrease MMPs and improve the treatment of brain ischemia." (PMID 35432799, 2021). "Secondary cerebral ischemia may develop several days after the primary injury, prompting MMP-9 increase as a part of the inflammatory response." (PMID 32575870, 2020). "Infiltrating neutrophils are believed to be the major source of active MMP-9 in cerebral ischemia." (PMID 32973660, 2020).
Cerebral ischemia (continued). "Naringenin also showed a neuroprotective profile in an animal model of brain ischemia, reducing apoptosis, inflammation, oxidative stress and neurological deficits through the modulation of claudin-5, MMP9, Nrf2, nucleotide oligomerization domain-like receptor 2 (NOD2) and NF-κB." (PMID 33383852, 2020). "By studying the expression of gelatinase in the brain from the sixth hour to 30th day after cerebral ischemia, Romanic, White, Arleth, Ohlstein, and Barone (1998) found that the expression of MMP‐9 increased significantly at 12 hr after ischemia, peaked at 24 hr, and lasted for several days." (PMID 31566928, 2019). "To assess the protective effects of AGNHW on the BBB integrity in the cerebral ischemia–reperfusion injury, we extracted the microvessels in the ipsilateral sides of the ischemic brains and examined the expression of MMP-9, MMP-2, and TJ proteins including ZO-1 and claudin-5." (PMID 31191319, 2019). "The findings of different MMP9 expression in the cortex and hippocampus could also be explained by the dynamic of changes after brain ischemia." (PMID 29849881, 2018). "HMGB1 may also trigger MMP9 upregulation in neurons and astrocytes in mouse brains after cerebral ischemia." (PMID 28348451, 2017). "Blood claudin-5 didn’t change in the early phase of cerebral ischemia while blood MMP-9 appeared to increase only marginally with prolongation of MCAO duration, suggesting the changes of these two molecules do not correlate well with the extent of early ischemic BBB damage." (PMID 28079139, 2017). "In contrast with previous reports showing that pharmacological activation of LXRs reduced MMP-9 protein expression following cerebral ischemia and suppressed MMP-9 mRNA and protein expression in macrophages, we found that MMP-9 activity was not altered by TO901317 after ICH." (PMID 26968836, 2016). "Our data suggested that during cerebral ischemia, activation of TRPV4 may increase the activated MMP-9 level, leading to the loss of ZO-1 and occludin." (PMID 25914628, 2015). "Since Angpt2, Bnip3, Mmp9, Pai1 and Vegfa genes are also important key players in cerebral ischemia, it is possible that the overall changes in their expression synergistically contribute in bringing about the beneficial effect of miR-335 in reducing the infarct volume." (PMID 26030758, 2015). "Peroxynitrite formation on microvessels colocalizes with MMP-9 expression after cerebral ischemia." (PMID 25147751, 2014). "MMP-9 (gelatinase B) attenuates the impenetrability of the blood-brain barrier by interrupting the endothelial basal lamina and as a consequence plays a role in cerebral ischemia, and the formation and rupture of cerebral aneurysms, as well as other CNS pathologies." (PMID 23966972, 2013). "Therefore, the present study was designed to examine the timecourse of upregulation of cerebrovascular proinflammatory cytokines and MMP-9 over 96 h in a rat SAH model that approximates late cerebral ischemia." (PMID 23259581, 2012). "However, further investigation of the potential mechanism by which ROCK regulates MMP9 during cerebral ischemia will be necessary to confirm our conclusion and will be the aim of our next study." (PMID 21541054, 2011). "Further study is required to better delineate MMP-9 mRNA expression patterns in blood, including the relationship with vascular reperfusion, duration of cerebral ischemia, treatment with tPA, and correlation with expression patterns of MMP-9 in cerebral tissue." (PMID 20406488, 2010). "However, several CNS pathologies such as cerebral ischemia, multiple sclerosis and Devic's neuromyelitis optica are also associated with increased MMP-2 and-9 levels and MMP-9 inhibition is beneficial against cerebral ischemia." (PMID 21176168, 2010). "Since the expression process and the regulation mechanism of MMP-9 have already been known, some therapeutics for cerebral ischemia could be available by regulating the expression and activation of MMP-9." (PMID 20514206, 2009).
Cerebral ischemia (continued). "The protease MMP-9 is specific for the structural components of the BBB, including type IV collagen and laminin, and it is associated with BBB breakdown in a mouse model of cerebral ischemia." (PMID 19893623, 2009). "As more information about MMP-9 we know, anti-MMP-9 therapy for cerebral ischemia could be designed more rationally." (PMID 20514206, 2009). "Whatever, in this article we just focus on MMP-9 in cerebral ischemia." (PMID 20514206, 2009). "These suggest that MMP-9 might be an important clinical target for the therapy of human cerebral ischemia." (PMID 20514206, 2009). "In addition, melatonin could inhibit the activation and expression of matrix metalloproteinase-9 (MMP-9) after cerebral ischemia, which would maintain the BBB integrity and reduce the infiltration of peripheral immune cells into lesion." (PMID 38932932, 2024). "In addition, MMP-3 can activate MMP-9 following cerebral ischemia." (PMID 39273389, 2024). "Furthermore, due to the excessive attention paid to BBB and MMP-9 in previous studies, exploring the mechanism of other MMPs in cerebral ischemia–reperfusion besides BBB destruction may be an idea for future research." (PMID 37483355, 2023). "As tPA activates MMP-9 and exacerbates hemorrhagic transformation after cerebral ischemia, we hypothesized that the use of SB-3CT in combination with tPA could mitigate neurotoxicity and extend the time window for treatment by tPA in a physiologically relevant model of AIS in mice." (PMID 29963617, 2018). "The increase in MMP-9 is further associated with different alterations, including excitotoxicity, neuronal damage, apoptosis, oxidative stress, interference with oxidative DNA repair mechanisms and BBB opening, leading to cerebral edema and hemorrhagic transformation after cerebral ischemia." (PMID 27445688, 2016). "Furthermore, vascular injury during brain ischemia may be due to activation of matrix metalloproteinase-9 (MMP-9)." (PMID 27445688, 2016). "Many studies indicate that cognitive dysfunctions may be associated with changes in MMP-9 activity, and show the importance of MMP-9 in cognitive dysfunctions of adult patients with dementia, cerebral ischemia or neuropsychiatric symptoms in autoimmune diseases." (PMID 24633733, 2015). "Together with our early reports, the present data indicate that during cerebral ischemia, blockage of TRPV4 may inhibit the activation of MMP-9 and the loss of ZO-1 and occludin, which helps to reduce the disruption of BBB integrity and the subsequent vasogenic brain edema and brain injury." (PMID 25914628, 2015). "However, an attenuated level of MMP-9 immunoreactivity was noted in both LBP1 and LBP10 group indicating that LBP could suppress the up-regulation of MMP-9 after cerebral ischemia." (PMID 22438957, 2012). "In addition, by use of the ROCK inhibitor fasudil, our study suggests a novel mechanism by which ROCK may upregulate MMP9 expression to contribute to microvascular damage during cerebral ischemia." (PMID 21541054, 2011). "During acute cerebral ischemia, α2-antiplasmin markedly enhances brain damage, disruption of the BBB, and increases the expression of MMP-9." (PMID 39001884, 2024). "Inhibiting the expression of MMP-9 can restore the integrity of TJs, reduce the permeability of the BBB, and improve the degree of cerebral edema after cerebral ischemia/reperfusion." (PMID 38927572, 2024). "However, a single dose of LGU (0.24, 2.16 mg/kg) in the tail vein can up-regulate the expression of tight junction proteins ZO-1 and occludin and inhibit the expression of MMP-9 after cerebral ischemia/reperfusion, suggesting that LGU may up-regulate tight junction proteins ZO-1 and occludin." (PMID 38927572, 2024). "Both MMP-9 and MMP-2 played a key role in the disruption of the BBB with subsequent hemorrhage, brain infarction, and edema after cerebral ischemia." (PMID 39273389, 2024).
Cerebral ischemia (continued). "Further, both MMP-2 and MMP-9 may attack the components of the basal lamina around the cerebral blood vessels, such as type IV collagen, laminin, and fibronectin, which contribute to the hemorrhagic transformation during the early stage of cerebral ischemia and reperfusion." (PMID 39273389, 2024). "MiR-21 was increased in patients with subarachnoid hemorrhage and cerebral ischemia, leading to increased ERK-stimulated MMP9 levels." (PMID 39407977, 2024). "The focus of the present study was to determine the time-dependent effects of the duration of ischemia and r-tPA treatment on brain injury, neurobehavioral outcomes, and the expression of MMPs (MMP-9, MMP-2, and MMP-3) in cerebral ischemia with reperfusion." (PMID 39273389, 2024). "MMP-9 acts on type IV collagen in the basement membrane of the endothelial walls, and elevated MMP-9 activity can lead to disruption of the blood-brain barrier (BBB), after cerebral ischemia and during inflammation." (PMID 39001884, 2024). "Recent studies have shown that, in cerebral ischemia, CD147 induces the production of matrix metalloproteinase 9 (MMP-9)." (PMID 38604775, 2024). "In our study, subacute administration of αPK reduced MMP-2 and MMP-9 levels and attenuated BBB breakdown and edema formation, supporting recovery after cerebral ischemia." (PMID 38872149, 2024). "3,5-di-CQA protects the blood-brain barrier from damage induced by cerebral ischemia by lowering iNOS expression, suppressing ROS/RNS generation, MMP-9 transcription and synthesis, and reducing MMP-9 degradation mechanisms on claudin-5, occludin, and ZO-1." (PMID 36678547, 2022). "MiRNA-149-5p also affects MMP-9 and superoxide dismutase in pericytes and improves BBB function following cerebral ischemia-reperfusion." (PMID 35871268, 2022). "We also observed that MFSCE enhanced the expression of tight and adherence junction proteins, whereas it decreased the expression of MMP-9, indicating its protective effects on the disruption of BBB and edema in cerebral ischemia." (PMID 35454994, 2022). "Another study has proved that OH-F NPs can reduce the transcription of IL-6 and MMP-9 to protect BBB integrity and relieve brain edema after cerebral ischemia-reperfusion injury." (PMID 35480961, 2022). "Inhibition of MMP-9 can alleviate dysfunction of the BBB, thereby reducing the degree of cerebral edema after cerebral ischemia." (PMID 35317197, 2022). "In cerebral ischemia, the increase of BBB permeability is mediated by activation of matrix metalloproteinase (MMP), and especially MMP-9." (PMID 35163322, 2022). "Rats with cerebral ischemia had decreased endothelial tight junction ZO-1 proteins, which was reversed by AG490 with increased ubiquitin Ubr1 E3 ligase and MMP-9 activity." (PMID 34943061, 2021). "Previous animal experiments have reported that cerebral ischemia results in the activation of MMP-2 and MMP-9 in brain tissue, leading to the degradation of occludin and destruction of the BBB." (PMID 32884584, 2020). "For example, blocking MMP activation or MMP-9 knock-out (KO) prevented degradation of CLN-5 and OCLN, and attenuated BBB disruption, in cerebral ischemia/reperfusion animal models." (PMID 30699952, 2019). "Based on these data, Ex-4 protects the integrity of the BBB partially by reducing VEGF-A and MMP-9 production in astrocytes, which were increased after OGD exposure or cerebral ischemia." (PMID 31779652, 2019). "XQ-1H suppressed neutrophils infiltration and inflammatory mediators, including cerebral ischemia induced intercellular adhesion molecule 1 (ICAM-1) and matrix metalloproteinase-9 (MMP-9), into the ischemic region of the brain." (PMID 31864312, 2019). "This is in contrasts to another study where MMP9 expression was significantly reduced in MCAs from rats subjected to middle cerebral artery occlusion (MCAO), another model of cerebral ischemia, and treated with U0126." (PMID 30978262, 2019).
Cerebral ischemia (continued). "MMP-9 is confirmed to be a key protease interfering with BBB leakage and natural evolution of cerebral ischemia." (PMID 29724240, 2018). "This study indicates that MMP-9 is secreted and localized at the ECM surrounding the endothelial cells after cerebral ischemia." (PMID 29963617, 2018). "The interactions between tPA and LRP1 or PDGFRα during cerebral ischemia increase the expression of MMP2 and MMP9." (PMID 30186167, 2018). "However, the relationship between ASK1 and MMP-9 after cerebral ischemia remains unknown." (PMID 27642277, 2016). "Since the brain injury that occurs after cerebral ischemia is a result of neuronal cell death with contributions both ASK1 and MMP-9 activation." (PMID 27642277, 2016). "The expression levels of MMP-9 and MMP-2 have been reported to start increasing from 12 h to 2 days and from 2 to 5 days after cerebral ischemia, respectively." (PMID 26637168, 2015). "We verified the expression of Angpt2, Bnip3, Mmp9, Pai1 and Vegfa genes since they were reported to be regulated by HIF-1α during cerebral ischemia." (PMID 26030758, 2015). "Among them, MMP-2 and MMP-9 are major MMPs that are involved in BBB injury and neuronal death after cerebral ischemia." (PMID 25914628, 2015). "In experimental models of brain ischemia, tissue inhibitor of metalloproteinases has been shown to protect BBB, inhibiting MMP9 activity." (PMID 26074872, 2015). "Matrix metalloproteinase-9 (MMP-9) inhibitor MMP-9 activation plays an important role in blood–brain barrier (BBB) disruption, resulting in brain edema and inflammation following brain ischemia." (PMID 24808942, 2014). "After cerebral ischemia, levels of MMP-2 and MMP-9 are increased, which plays an active role in the formation of brain edema and the secondary brain injury." (PMID 23459987, 2013). "Mounting evidence indicates that MMPs, in particular MMP-9 and -2, contribute to BBB disruption and vasogenic edema, hemorrhagic transformation, and cell death induced by cerebral ischemia and reperfusion." (PMID 23710225, 2013). "Among the various MMPs, metalloproteinase-9 (MMP-9), also known as gelatinase B, is thought to play an important role in BBB disruption after cerebral ischemia and inflammation." (PMID 23829879, 2013). "In conclusion, the current study demonstrated that XXMD, as a drug of multiple targets, improved neurological function and exerted a protective effect on the BBB by downregulation of MMP-9, -2, and VEGF after cerebral ischemia and reperfusion injury." (PMID 23710225, 2013). "MMP9, through degradation of the ECM, can alter BBB permeability but is frequently increased after brain ischemia." (PMID 23862012, 2013). "Our results established a correlation among ROCK, brain EB content, laminin expression and MMP9 expression following MCAO, demonstrating the protective effects of fasudil on microvascular damage during cerebral ischemia." (PMID 21541054, 2011). "Overall, the neurological outcome in cerebral ischemia is improved by minocycline through MMP-2 and MMP-9 downregulation." (PMID 21110846, 2010). "Our data indicate, for the first time, that the expression of MMP-9 and TIMP-1 in cerebral blood vessel smooth muscle cells is enhanced after cerebral ischemia and that this enhancement is a transcriptional event." (PMID 19497125, 2009). "MMP-9 promotes injury of the BBB, vasogenic edema formation, infarct size and hemorrhagic transformation in the acute phase after cerebral ischemia." (PMID 20514206, 2009). "Furthermore, in the cerebral ischemia‐reperfusion model, neuroinflammation mediated by MMP‐3 and MMP9 is important for white matter damage and oligodendrocyte apoptosis." (PMID 40864831, 2025). "Different levels of mmp-9 gene expression affect neuronal excitability affected by cerebral ischemia: lack of the active form of the enzyme in MMP-9 KO mice reduces, while overexpression of MMP-9 intensifies susceptibility to the chemoconvulsive agent, PTZ." (PMID 38255970, 2024).